CFTR (CF transmembrane conductance regulator)
Diseases named in the same sentence as CFTR in open-access papers (continued):
Sharing a sentence is not in itself a finding about the gene and the disease.
infection (continued). "Our results reinforce the hypothesis of a cross-talk between lung and gut microbiota in relation to P. aeruginosa chronic infection and CFTR mutation and emphasize the need of animal models to mechanistically decipher the influence of infection on whole host physiology." (PMID 34830048, 2021). "For example, we thought that the best test of an infection clearance regime would target chronically infected subjects with highly responsive CFTR mutations and that starting modulators and antibiotics in rapid succession might reduce time for bacterial adaptation." (PMID 34903059, 2021). "Collectively, these studies suggest that loss of functional CFTR and the compound effects of ionic imbalance could prime the innate immune system in advance of infection, leading to heightened inflammatory responses and pro-apoptotic priming when an infection is present." (PMID 32367193, 2020). "To determine whether an impaired oxidative defense is involved in defective CFTR-associated reduced bacterial killing in early infection stages, we examined whether heat-killed and intact Mabs induce intracellular ROS production in macrophages using the CellROX dye." (PMID 30759393, 2019). "Accordingly, challenged CF mice elicit a sustained inflammatory response that could allow for investigations into the relationship between inflammation and infection in a CFTR-deficient lung, as well as trialling of novel anti-inflammatory and antibiotic therapies." (PMID 29609604, 2018). "Despite the clinical benefits of CFTR modulators, airway damage and established infections often remain." (PMID 42198683, 2026). "CF is recognised as a neutrophilic airways disease and consistent with this we found that neutrophil recruitment to the airways was significantly increased in CFTR-/- mice compared to wild type (WT) controls at both 6- and 18-hours post-infection (p ≤ 0.05)." (PMID 39903773, 2025). "Together, these findings highlight how CFTR dysfunction disrupts normal mucociliary function and host defenses, perpetuating the cycle of infection and inflammation in CF airways." (PMID 40227282, 2025). "CFUs in bronchoalveolar lavage fluid from infected CFTR-/- and WT mice, obtained 6- and 18– hours post-infection, were assessed." (PMID 39903773, 2025). "Infection studies were limited to a CFTR functional mouse model, as improvements to CF lung infection models in mice remain in progress." (PMID 41198444, 2025). "Ultimately, a comprehensive approach that integrates immune modulation, microbiome management, and infection prevention strategies is necessary to fully optimize clinical outcomes in the era of highly effective CFTR modulators." (PMID 41154689, 2025). "In this study we aimed to evaluate the role of the CFTR protein in the inflammatory response to, and induction of cell death by A. fumigatus in both acute and chronic murine models of infection and cells from pwCF." (PMID 39903773, 2025). "ETI facilitates the proper folding, apical transport, and activation of CFTR to restore epithelial ion transport, which improves mucociliary function and attenuates infection and inflammation." (PMID 41212059, 2025). "The cystic fibrosis transmembrane conductance regulator (CFTR) is a cAMP-dependent Cl− channel that regulates the host immune defense against pathogen infection, such as SARS-CoV-2." (PMID 40872762, 2025). "This revealed increased CXCL1 release at 6 hours post-infection in CFTR-/- mice compared to controls." (PMID 39903773, 2025). "One study that evaluated the bacterial density of P. aeruginosa reported a decrease in CF patients receiving CFTR modulators with concurrent inhaled antibiotics, with very few patients reporting a cleared infection." (PMID 40700326, 2025). "Understanding the complex interaction between CFTR modulation, immune responses, and microbiota dynamics is crucial for developing adjunctive strategies aimed at infection control." (PMID 41154689, 2025).
infection (continued). "While the direct physiological impacts of CFTR mutation are well characterized, less is known regarding the consequences of CFTR mutation on the epithelial response to the non-pathogenic bacteria commonly inhabiting the CF lungs, and whether this helps or hinders infection control." (PMID 41198444, 2025). "The airway presents a more complex GSH profile; while BALF from CF patients and CFTR-deficient models typically shows depleted GSH, exacerbated by infection, sputum studies have surprisingly reported higher total GSH." (PMID 40740993, 2025). "In another set of reports from the Kremer research group, it was shown that the Mab-specific phage Muddy can synergize with antibiotics and help control Mab infection in a CFTR zebrafish model, but only if the innate immune system is intact." (PMID 40415550, 2025). "CF results from CFTR protein dysfunction leading to dehydrated secretions, ductal obstruction and infection." (PMID 41383369, 2025). "In this study, we have further demonstrated that not only do pwCF remain colonized with P. aeruginosa after CFTR modulation but the same clonal lineages persist, as opposed to the eradication of preexisting strains and establishment of new infections." (PMID 38442240, 2024). "Together, these findings highlight that even in the CFTR modulator therapy era, there is an ongoing need for new treatment strategies targeting both neutrophilic inflammation and infection in CF lung disease." (PMID 39293854, 2024). "For both WT and CFTR KO cells, we subtracted the percentage of p21-positive cells in mock infection conditions from the percentage detected following SARS-CoV-2 infection." (PMID 38892373, 2024). "Some studies document changes in mucin sialylation as a result of infection in CF, while others have reported altered mucin sialylation in CFTR−/− newborn piglets before the onset of inflammation or infection." (PMID 38853971, 2024). "The p.Phe508del-CFTR protein is retained in the endoplasmic reticulum (ER) and together with inflammation and infection triggers the Unfolded Protein Response (UPR)." (PMID 38247876, 2024). "Results show that several rare pathogenic/likely pathogenic genomic variants in genes CFTR, MASP2, MEFV, TNFRSF13B, and RNASEL likely contribute to the severe infection outcomes in our patient cohort." (PMID 39062917, 2024). "The vicious cycle that is established by the defective CFTR function, recurrent infections and chronic inflammation ultimately results in lung damage and failure." (PMID 38721278, 2024). "Late in the infection, CFTR WT cells showed single-membrane, matrix-free vesicles containing dense particles, identified according to their size and appearance as virion-containing vesicles." (PMID 38892373, 2024). "Our results found that the SGK1 activity was up-regulated at 4 and 24 h post-infection, and the CFTR inhibitors, Glyh-101, CFTRi-172, and IOWH-032, attenuated the SGK1 activity in infected cells." (PMID 39205282, 2024). "The use of CF transmembrane conductance regulator (CFTR) modulator therapies has decreased some of the CF burden of infection by delaying airway colonisation." (PMID 39493847, 2024). "A remarkable reversal of the situation was found after SARS-CoV-2 infection, where the percentage of p21-IR cells was higher in WT cells than in CFTR KO cells at all time points, with a statistically significant increase at 24 h post infection (hpi)." (PMID 38892373, 2024). "Nevertheless, the IHC results showed a reactivity to the N SARS-CoV-2 protein antibody in both WT cells and CFTR KO cells at all time points of the infection tested, although the reactivity was more pronounced in WT cells than in KO cells." (PMID 38892373, 2024). "CFTR mutant mice and their WT littermates were intratracheally infected with S. maltophilia and P. aeruginosa alone, or in a concurrent polymicrobial infection." (PMID 36748431, 2023).
infection (continued). "Our findings that inflammation persisted despite a reduced bacterial burden in the presence of CFTR correctors indicate that the infection induces some lasting effect, perhaps lasting damage that is not related to epithelial culture resistance." (PMID 37998353, 2023). "It has previously been demonstrated that infection with P. aeruginosa bacteria reduce the functional expression of WT-CFTR or Orkambi®-rescued F508del-CFTR in CFBE and primary epithelial cells." (PMID 37443798, 2023). "Elastase is more prominent during early infection and was found to decrease both the residual CFTR activity and expression, making it a direct contributor to worsening infection and CF pathology." (PMID 36902441, 2023). "Chloride secretory activity was reduced in the cecum and distal colon during infection by decreased CaCC and CFTR function, respectively." (PMID 37350393, 2023). "Considering that most CF patients are likely colonized by bacteria when CFTR modulator therapy is initiated, there is a clinical need to assess the impact of infection on drug metabolism to determine the correct dosage." (PMID 36625583, 2023). "This contrasts with studies of prior CFTR modulators, that showed rapid improvement, but then a return of infection and lung function decline." (PMID 37841851, 2023). "The effect of LPS and infection on lung function and remodeling in this smooth muscle-specific CFTR knockout model is a direction for future study." (PMID 37568151, 2023). "Our cohort was heterogeneous regarding several baseline characteristics (ppFEV1, genotype, infection status, previous CFTR modulator therapy)." (PMID 36875141, 2023). "While the prevalence of lung infections decreases with highly effective CFTR modulators, prospective studies suggest that infection persists after initiation of ivacaftor or elexacaftor/tezacaftor/ivacaftor." (PMID 37891457, 2023). "When CFTR function is ablated or impaired, airways develop thickened, adherent mucus that contributes to a vicious cycle of infection and inflammation." (PMID 37998353, 2023). "Characterising infection status has become more difficult because sputum samples are less available due to the effect of CFTR modulators on mucus retention." (PMID 36631132, 2023). "Here, we examine the efficacy of CFTR modulator therapies in primary CF airway epithelial cultures with prolonged luminal infection." (PMID 37998353, 2023). "No major difference in ACE-2 expression was detected before infection between wild-type and CFTR-modified cells, while a higher expression in wild-type compared to CFTR-modified cells was detectable at 72 h post-infection." (PMID 35456026, 2022). "To study the transplanted CF host–Af relationship, we studied Af infection in our OTT model using a CFTR−/− mouse as the transplant recipient compared to wild type (WT) control transplant recipients." (PMID 35887506, 2022). "In particular, CFTR knockout (KO) and wild-type mice were infected with M. abscessus and, starting from day 8 after infection, treated 3 times per week for 4 consecutive weeks by intranasal inoculation of 105 ABLs carrying PI5P." (PMID 35080463, 2022). "CFTR-KD epithelia exhibited strong ASL volume reduction, enhanced susceptibility to infection, and reduced junctional integrity." (PMID 35563895, 2022). "Influenza M2 membrane protein, which has ion channel activity, was shown to inhibit CFTR during infection." (PMID 35229638, 2022). "These systems enable to study intercellular communication and incorporate downstream consequences of CFTR dysfunction in the same platform, including inflammation, infection and mucus burden." (PMID 36013270, 2022). "Infection with virulent SARS-CoV-WT significantly reduced the expression of CFTR in lungs of mice, especially at 4 days p.i., overlapping with the most prominent pulmonary edema." (PMID 35229638, 2022).
infection (continued). "Although the significance and molecular basis of this dysregulation remain unclear, mutations in CFTR can not only affect the innate immune function of airway epithelial cells but also alter the innate immunity that contributes to recurrent and progressive infection in CF." (PMID 35315363, 2022). "We, thus, analyzed at the ultrastructural level the morphological effects of SARS-CoV-2 infection on wild-type (WT) and F508del (ΔF) CFTR-expressing CFBE41o- cells at early and late time points post infection." (PMID 36077122, 2022). "This review aims to summarize important advances in infection and inflammation as well as the effect of new treatments modulating the Cystic Fibrosis Transmembrane Conductance Regulator (CFTR) protein." (PMID 36553341, 2022). "PAO1 proliferated in the apical compartments, resulting in a 5-log and 7-log increase in CFU count in the CFTR-CTL and CFTR-KD cultures, respectively, 24 h post-infection." (PMID 35563895, 2022). "At 24 h post-infection, the macroscopic epithelial integrity was still preserved in both the hydrated CFTR-KD cell conditions while more variability was observed in the TEER measurements." (PMID 35563895, 2022). "Traditional therapies target the downstream effects of CFTR dysfunction and include symptom management through airway clearance and, the prevention and treatment of infection with antimicrobials." (PMID 35408875, 2022). "Further studies are needed to determine CFTR’s role in phagosome maturation and acidification during infection with other CF pathogens." (PMID 35887098, 2022). "At 16 h post-infection, ΔlasR already induced damage on the CFTR-KD epithelium and a strong TEER decrease." (PMID 35563895, 2022). "Vector-specific CFTR mRNA expression and the viral genome were detected in the macaques up to 180 days after infection." (PMID 36304167, 2022). "The recent development of CFTR modulators seems to alter the milieu in the CF airways reducing inflammation and possibly infection, and it is expected to alter the long-term outcomes of the disease dramatically." (PMID 36553341, 2022). "To confirm the vulnerability of the CFTR-KD cells regarding CF context, we performed additional infections with three PAO1 mutant strains, deleted for specific virulence factors commonly found in CF patients." (PMID 35563895, 2022). "Due to infection with pathogens, the functional disruption of ion transporters, such as cystic fibrosis transmembrane conductance regulator (CFTR) and epithelial Na+/H+ exchanger SLC9A3, can result in diarrhea, malabsorption, and inflammation of the intestine." (PMID 33535430, 2021). "Controls were older than cases, whereas the two groups were comparable in terms of sex, CFTR genotype, comorbidities, CF-maintenance therapy, and respiratory function prior to the infection." (PMID 33984027, 2021). "Lymphocytes, monocytes/macrophages, neutrophils, and dendritic cells of patients with CF express functional CFTR and are directly affected by altered CFTR expression/function, impairing their ability to resolve infections and inflammation." (PMID 34943888, 2021). "This allowed us to report a stepwise dissection of M. abscessus infection in an animal depleted of CFTR to elucidate the biological implication of CFTR in innate immunity to these infections." (PMID 34530447, 2021). "The results highlight the important role infection plays in the ORKAMBI®-mediated rescue F508del-CFTR function." (PMID 32092967, 2020). "There were significant reductions in IL-8, IL-6, and TNF-α production during infection in CFTR KO MDMs when compared to media alone or empty vector transfection." (PMID 32973772, 2020). "As immunosuppression increases the risk of infection and/or malignancy, which are both already increased in people with CF, possible alternative medications may involve the blockade of individual cytokine or inflammatory pathways, or the use of novel CFTR modulators." (PMID 33282799, 2020).
infection (continued). "While CFTR mutant and knockout mice were developed shortly after discovery of the CFTR gene, their use as animal models for CF lung disease is controversial as they lack a robust CF lung phenotype of spontaneous infection and disease." (PMID 32318073, 2020). "mRNA levels for all three cytokines increased upon infection of F508del-CFTR cells with PAO1 and decreased with subsequent treatment with increasing doses of 6K-F17." (PMID 32092967, 2020). "As previously studied, we confirmed that infection with PAO1 bacteria decreases F508del-CFTR function." (PMID 32092967, 2020). "These embryos also possessed fewer granulomas and granulomas displayed a disorganized structure, suggesting that CFTR is also an important determinant of infection containment within the granuloma microenvironment." (PMID 32850470, 2020). "A recent comprehensive article summarizes the role of dysfunctional CFTR in the controlling cellular signaling pathways used by innate immune cells for combating infections such as airway epithelial cells, neutrophils, monocytes, and macrophages." (PMID 32847034, 2020). "This study suggests that many aspects of CF macrophage dysfunction are CFTR-dependent, which is important as we develop new approaches to regulate immune responses to infection in CF." (PMID 32973772, 2020). "Here, we bridge CFTR-modulators to infection by defining the impact of these therapies on airway microbiology and clinical response in CF patients." (PMID 32234058, 2020). "The presence of sterile inflammation has also been observed in animal models, notably in CFTR-knockout ferrets that show signs of neutrophil-mediated inflammation despite being infection-free." (PMID 32982730, 2020). "Our studies provide the first in vitro evidence that anti-infectives—in addition to eliminating growth of lab and clinical strains of P. aeruginosa—help to restore infection-mediated losses in CFTR function." (PMID 32092967, 2020). "We show the negative impact that P. aeruginosa infections have on WT- and F508del-CFTR function, and how the application of the anti-infectives tobramycin and 6K-F17 reverses infection-mediated decreases in CFTR function." (PMID 32092967, 2020). "When exposed to infection, the CFTR protein acts as a receptor for P. aeruginosa in AECs, and it is thought to be involved in uptake and clearance of this pathogen." (PMID 32367193, 2020). "Strikingly, in CFTR-depleted embryos, there was an enhanced proportion of embryos with cords at both 2 and 4 dpi when compared to wild-type infection." (PMID 32850470, 2020). "M. fortuitum-infected CFTR-depleted zebrafish rapidly succumbed to infection, reflecting a hypersusceptibility phenotype to this mycobacterial species in CF and providing a first glance into the vulnerability of CF patients to M. fortuitum infection." (PMID 32850470, 2020). "In this review, we explore the effects of CFTR modulators on airway inflammation, infection, and their influence on the impaired pulmonary host defences associated with CF lung disease." (PMID 32887484, 2020). "Despite exciting developments in the field of CFTR modulators, there remains an unmet need to develop therapies that ameliorate ongoing problems with inflammation and infection." (PMID 32569477, 2020). "HBE cells were pre-incubated with VX-809 for 24 h prior to PAO1 infection and treatment with 6K-F17 or tobramycin to assess the impact of the corrector VX-809 on the infection rate and on F508del-CFTR function." (PMID 32092967, 2020). "The coupling of the microbial cell viability assay with the FLIPR membrane depolarization assay provides a direct link between infection status and diminishing CFTR function." (PMID 32092967, 2020). "Pre-existing infections with clinical strains of P. aeruginosa emphasize the importance of coupling ORKAMBI® treatment with anti-infectives to improve the rescue of F508del-CFTR function in vitro." (PMID 32092967, 2020).